MTOR (mechanistic target of rapamycin kinase)
Diseases named in the same sentence as MTOR in open-access papers (continued):
Sharing a sentence is not in itself a finding about the gene and the disease.
cancer (continued). "Another instance of a targeted therapy in clinical use is everolimus (AfinitorTM); this drug inhibits the mammalian target of rapamycin (mTOR) pathway, which is involved in the regulation of the cell cycle, thereby inhibiting cancer cell growth." (PMID 32411603, 2020). "The mTOR pathway regulates energy homeostasis and engages in cancer cell survival in cellular metabolic stress such as depletion in nutrients and energy." (PMID 32318579, 2020). "In such a situation, the downstream effectors of the PI3K/Akt pathway such as mTOR, can be a target for the treatment of various cancers." (PMID 33292283, 2020). "Rapamycin, in further analogy with PI3K inhibitors, has the potential to be an anti-cancer drug via its inhibition of mTOR, a signaling molecule downstream of PI3K which promotes cell growth and inhibits apoptosis." (PMID 33270630, 2020). "For instance, targeting both PI3K and mTOR with NVP-BEZ235, a dual PI3K/mTOR inhibitor, resulted in an antiproliferative and antitumoral activity in cancer cells." (PMID 33123479, 2020). "Both ATIC and BZW2 are considered human oncogenic genes that promote cancer proliferation and migration through mTOR signaling." (PMID 32559205, 2020). "Function enrichment analysis showed the genes in the ceRNA network participate in several KEGG pathways; including T cell receptor signaling pathway, MicroRNAs in cancer progression pathway, FoxO signaling pathway, Autophagy-animal and mTOR signaling pathways." (PMID 32419983, 2020). "The evidence provided by this review shows that sensitivity to DNA-PKcs inhibitors is correlated with the activity of several signaling pathways, in particular the PI3K (Phosphoinositide 3-kinase)/AKT/mTOR pathway and epithelial/mesenchymal state in cancer." (PMID 33207636, 2020). "The best-established mechanism of mTOR activation in cancer is via PI3K/Akt signaling, but mTOR activity can also be stimulated by CDK4 and PIM kinases." (PMID 32391118, 2020). "p70S6 kinase (p70S6K), a serine/threonine protein kinase, phosphorylated through the PI3K/mTOR pathway, was reported to play a role in cellular proliferation, survival, motility metastasis, and chemotherapy drug resistance in cancer cells." (PMID 32155920, 2020). "Because the mTOR signaling pathway is active in most human cancers, scientists have developed first and second-generation mTOR inhibitors for cancer treatment." (PMID 32175074, 2020). "KEGG analysis revealed that 111 pathways, such as Calcium, mTOR, Wnt, Notch signal pathway, neuroactive ligand-receptor interaction, neurotrophin signaling pathway and cancer, were involved." (PMID 32216802, 2020). "The dual PI3k/mTOR inhibitor BEZ235 has been approved by the FDA for the treatment of various cancers." (PMID 32826876, 2020). "Here, we found that drug-resistant cancer cells (those surviving anticancer drug treatment) show induction of the autophagy process with mTOR activation accompanying an increase in ATP production as a result of increased OxPhos." (PMID 32883024, 2020). "In contrast to the mechanisms described for different cancer types, our female mice with hepatocyte-specific Hh KO exhibit reduced mTOR activity, as was shown through reduced ATP production and mTOR-related gene expression." (PMID 32751882, 2020). "Considering the overlapping effect of these kinases on normal and cancerous cellular function, an inhibitor that targets both the PIM and the PI3K/AKT/mTOR pathway would have potential utility in cancer treatment." (PMID 32042115, 2020). "The PI3K/AKT/mTOR pathway is involved in the regulation of cancer cellular processes, including cell proliferation, migration, invasion, and survival." (PMID 33116125, 2020). "It has been shown that the use of PI3K and mTOR inhibitors in combination leads to increased inhibition of cancer cell proliferation and tumor growth." (PMID 33659215, 2020).
cancer (continued). "The immunosuppressant drug rapamycin and its analogs that inhibit mTOR are currently being evaluated for their potential as anti-cancer agents, albeit with limited efficacy." (PMID 32054043, 2020). "A combination therapy with inhibitors of both mTOR and Wnt pathways warrants further study, as together they play a key role in cancer metastasis formation and chemoresistance." (PMID 32676162, 2020). "RSK and mTOR are important drug targets for diseases including cancer, cardiovascular and neurological disorders." (PMID 32605013, 2020). "PI3K/Akt encourage expression of lipogenesis genes in various cell types, while mTOR is a key controller of protein synthesis in cancer cells." (PMID 32318579, 2020). "The possible antitumor effect of metformin in the form of inhibiting the proliferation, invasiveness, and migration of cancer cells by regulating the AMPK/mTOR pathway has already been observed in pancreatic cancer and lung cancer." (PMID 31952173, 2020). "Rapid development of resistance to rapamycin in cancer cells accelerated efforts to introduce novel generations of mTOR inhibitors." (PMID 33173419, 2020). "To expand our knowledge in this area, we are interested in searching for new and previously uncharacterized component(s) of the mTOR signaling network in advanced EGFR-mut cancers." (PMID 32923403, 2020). "The AKT/mTOR pathway is very important pathway that regulates the cell cycle and is involved in cell proliferation, cellular quiescence, and many forms of cancers." (PMID 33053749, 2020). "In the mTOR pathway, the alteration of crucial members was the highest in GI and development tract cancer (43.4% across patients) than in other tumor types." (PMID 32863943, 2020). "Research in different kinds of cancer has focused mainly on mTOR or the Akt/mTOR pathway, which are signaling cascades shared between translation and autophagy." (PMID 32232004, 2020). "Chronic treatment with the mTOR inhibitor, everolimus, fails long-term in preventing tumor growth and dissemination in cancer patients." (PMID 32759798, 2020). "In terms of its cellular effects, some studies showed that Rab1A promoted cellular proliferation, invasion and EMT process through activation of mTOR signaling in several cancers." (PMID 33068388, 2020). "Inhibiting the PI3K/mTOR pathway has been shown to be effective in many cancers, and multiple PI3K/mTOR inhibitors are currently in clinical trials." (PMID 32295632, 2020). "Based on these reasons, mTOR is currently being studied as a potential target for anti-cancer therapy." (PMID 32751889, 2020). "One possible explanation for this observation is that metformin and insulin are thought to reduce the activity of mTOR, which blocks progression of the cell cycle and cancer growth." (PMID 32539807, 2020). "The inhibitory effects of abemaciclib on mTOR signaling in cancer cell lines and xenograft models all occur at drug concentrations that are readily achieved in patients receiving the recommended dose." (PMID 32391118, 2020). "The activated PI3K/AKT/mTOR pathway can decrease the BCL-2 homology domain (BH3) mimetic effectiveness in cancer cells by upregulating anti-apoptotic BCL-2 family members, such as myeloid cell leukemia-1 (MCL-1) and B-cell lymphoma-extra large (BCL-XL)." (PMID 32131492, 2020). "DGKs control cancer cell survival, proliferation, and angiogenesis by regulating Akt/mTOR and MAPK/ERK pathways." (PMID 32722576, 2020). "HIF-1α is often regulated through several oncogenic cellular molecules like the Akt/mammalian target of rapamycin (mTOR), which is found to be upregulated in cancer." (PMID 33014057, 2020).
cancer (continued). "Quercetin is a potent inducer of autophagy in many cancer cell lines 81, 82, 83 and can induce autophagy‐mediated apoptosis in certain cancer cells through the inhibition of proteasomal activity and mTOR signaling." (PMID 31568659, 2020). "Although HIF-1α constitutes a potent hypoxic response mechanism, other pathways such as the phosphatidylinositol 3-kinases (PI3K)-Akt-mTOR pathway and Wnt/ß–catenin also participate in the adaptation of cancer cells to hypoxic conditions." (PMID 32024881, 2020). "In this regard, recent development in campaigns aimed to generate dual mTOR complex inhibitors and their functional validation in experimental trials has raised hopes in advancing our ability to treat lethal cancers." (PMID 33371210, 2020). "And FBXW7 targets several proteins with critical roles in the hallmarks of cancer, such as cyclin E, Notch, mTOR, c-MYC, etc." (PMID 32239181, 2020). "Dysregulation of mTOR signaling often occurs in a variety of cancer, rendering it a promising target in cancer therapy." (PMID 33116125, 2020). "The phosphoinositide 3-kinase (PI3K)/Akt/mammalian target of rapamycin (mTOR) is the most commonly upregulated pathway in human cancers." (PMID 32605290, 2020). "To date, numerous second-generation mTOR inhibitors have been developed to efficiently treat cancers." (PMID 33067464, 2020). "The molecules along the signaling network of PI3K/ATK/mTOR pathway regulate most cellular processes involved in cancer development, including cell cycle progression, survival, metabolism, motility and immunity." (PMID 32483262, 2020). "Activation of autophagy by the PI3K/AKT/mTOR inhibitors not only enhances treatment sensitivity but also leads to cell survival when drug resistance develops in cancer cells." (PMID 33123479, 2020). "Other studies demonstrate that metformin inhibit mammalian target of rapamycin (mTOR) through activation of AMPK resulting in reduced cancer cells proliferation." (PMID 33092251, 2020). "The cancer-intrinsic PD-1 promotes malignant proliferation by upregulating mammalian target of rapamycin (mTOR) signaling." (PMID 32944392, 2020). "This is significant since many of the cancer prevention effects of CR are thought to involve repression of the pro-proliferation anti-apoptotic IGF-1/AKT/mTOR signaling axis." (PMID 32211051, 2020). "Dysregulated mTOR signaling has been demonstrated in various cancers, which made mTOR a promising target and facilitated the development of derivatives of rapamycin, a naturally occurring mTOR inhibitor." (PMID 33628728, 2020). "For example, activation of the mTOR pathway initiates metabolic symbiosis in cancer cells which thus become resistant to VEGF inhibitors." (PMID 33153193, 2020). "Phosphatase and tensin homolog (PTEN) is the second most frequently mutated gene in cancers including HCC and encodes a phosphatase protein that returns the PI3K/Akt/mTOR pathway to its inactivated state." (PMID 32831114, 2020). "Since it is well known that inhibition of LAT1 suppresses mTOR signaling that is associated with the decreased growth of the cancer cells, the aim in this study was to evaluate if LAT1-inhibitor 1 can affect the total amount of mTOR in MCF-7 cells." (PMID 32405891, 2020). "Following the same logic, we found that miR-141-3p targets most of the survival and metabolism related pathways, including the MAPK signaling pathway, mTOR signaling pathway, ErbB signaling pathway, and pathways in cancer." (PMID 33133155, 2020). "Since Akt and mammalian target of rapamycin (mTOR) regulate cell metabolism, growth, proliferation, and survival, these molecules are considered candidates for therapeutic targets for cancers." (PMID 32630642, 2020). "Pathway dysregulation affiliated with PI3K/Akt/mTOR has been reported to be detrimental in more than 50% of all human cancers." (PMID 33292283, 2020).
cancer (continued). "The mTOR pathway is one of the major nutrient-sensitive cascades regulating growth, metabolism, the aging process and diseases like cancer and epilepsy, in mammals." (PMID 33027921, 2020). "Overactivation of mTOR signaling significantly contributes to the initiation and development of tumors and mTOR activity was found to be deregulated in many types of cancer including HCC." (PMID 31898515, 2020). "On the other hand, the PI3K/Akt/mTOR pathway has been reported to be activated in many other cancers." (PMID 32521808, 2020). "PD-L1 can also regulate cancer cell metabolism through the mTOR pathway and extracellular glucose availability." (PMID 32599891, 2020). "mTOR signaling pattern helps the cancer cells and CSCs to maintain stem cell characteristics like; self-renewal, survival and cell proliferation." (PMID 32351329, 2020). "Cellular abrasions in the phosphoinositide 3-kinase/AKT/mammalian target of rapamyacin (PI3K/AKT/mTOR) signaling pathway have been considered as a promoting factor in the progression of various cancers." (PMID 33292283, 2020). "PI3K/AKT/mTOR and AMPK/mTOR pathways are two important signaling cascades that are involved in regulating aerobic glycolysis of cancer cells." (PMID 32943998, 2020). "Given its central role in co-ordinating metabolism, mTOR is at the crossroads between anabolic pathways and mitogenic signalling of cancer cells." (PMID 31819197, 2020). "The next step is the activation of mTOR signaling, which promotes both the migration and proliferation of cancer cells." (PMID 32756305, 2020). "mTOR inhibitors are a Food and Drug Administration approved targeted therapy for cancer patients, including NSCLC, and is currently under extensive clinical studies." (PMID 32753611, 2020). "Intriguingly, it has been reported that mTOR inhibition increases ERK activity in some cancer models, and this event is likely due to the existence of a negative feedback loop between the PI3K/mTOR axis and MAPK/ERK pathway." (PMID 32823532, 2020). "As we linked all the interactions between the core-clock genes, cancer hallmarks and circadian drug target genes, we observed that AKT1 and MTOR were circadian expressed, drug target genes, in both cell lines." (PMID 32295075, 2020). "Tumor suppression in vivo also confirmed that autophagy restraint via the PI3K/Akt/mTOR signaling pathway contributed to the anti-cancer activity of BJE, thereby highlighting its clinical importance as a novel natural agent against TNBC." (PMID 32411003, 2020). "In particular, we showed that MTOR and AKT1 are oscillating in our data sets and associated to the circadian clock, cancer hallmarks and circadian drug targets." (PMID 32295075, 2020). "Increasing evidence demonstrates that these synthetic compounds decrease cancer stem cell-like phenotype as well as invasive potential by targeting upstream regulators of the mTOR signaling in GSCs." (PMID 33092261, 2020). "In many human cancers, mTOR signaling is hyperactivated, leading to increased tumorigenesis, increased tumor progression, and decreased survival." (PMID 33037092, 2020). "In the second comparison (SCC vs. ADJ), in addition to several cancer-related pathways, we also observed six pathways that are exclusive of this comparison (e.g., mTOR signaling pathway)." (PMID 33182525, 2020). "On the other hand, FDA approved four PI3K and three mTOR inhibitors for clinical cancer therapy, and two Akt inhibitors are in phase III clinical trials for combination therapy of breast and colorectal cancers." (PMID 32106627, 2020). "Most recently, novel strategies to treat cancer have been developed that utilize nanoparticles to target mTOR and AMP-activated protein kinase (AMPK) pathways." (PMID 32232004, 2020). "Increased recognition of the importance of the mTOR pathway in cancer treatment has called for exploration of mTOR inhibitors as radio-sensitisers for treating many types of cancer." (PMID 31959810, 2020).
cancer (continued). "Despite these observations, other studies and early clinical trials highlighted that PI3K/mTOR inhibitors suppress the MEK/ERK pathway in other cancer types." (PMID 32823532, 2020). "Metformin activates AMPK via LKB1, which leads to the inhibition of mTOR signaling and its major downstream effectors, the 4E-BPs and p70S6Ks, and the inhibition of global protein synthesis and proliferation in various cancer cell lines." (PMID 32825834, 2020). "Next, we used the TPRMET-NIH3T3 cell line to analyze the effects of the combined treatments of MET- and mTOR-targeted MET on MET-driven cancer cells." (PMID 32764535, 2020). "First, we identified several DEGs in cancer-related signaling pathways (Wnt, mTOR, MAPK signaling pathways) in the KEGG results, and based on these signaling pathways we screened the relevant molecules in the ceRNA network to build subgroups." (PMID 32196072, 2020). "In particular, Sestrin2, which mainly protects cells from oxidative stress and acts as a leucine sensor protein in mammalian target of rapamycin (mTOR) signaling, is thought to affect various cancers in different ways." (PMID 32882793, 2020). "Activation of the Akt/mTOR pathway is often correlated with tumor growth, while the suppression of Akt shows promising tools for cancer cell treatment." (PMID 32401800, 2020). "The mTOR pathway is also a key regulator of cell growth and proliferation, and in various cancers mTOR hyperactivation is often detected, which markedly contributes to cancer progression." (PMID 31894839, 2020). "Since the PI3K/Akt/mTOR signaling pathway is often dysregulated in several human malignancies, inhibitor targeting of this pathway holds immense interest in cancer treatment." (PMID 32466169, 2020). "The association of these proteins with DEK-NUP214 was proposed to promote activation of several cancer associated pathways, such as AKT/mTOR, Src family kinase (SFK), ABL1, and c-MYC pathways." (PMID 32664447, 2020). "It inhibits cell proliferation and induces autophagic cell death by inhibiting PKM2-mediated cancer cell metabolism via the PI3K/Akt/mTOR pathway." (PMID 32398958, 2020). "Similar LY effects on mTOR functional state were described for different types of human cancer and normal cells including MSC." (PMID 31951594, 2020). "The utilization of AZD2014 as both a pan-mTOR inhibitor and photosensitiser provides a novel strategy for combating cancer and tumour growth." (PMID 33142217, 2020). "Another downstream target protein for the PI3K/Akt signaling pathway is the mammalian target of rapamycin (mTOR), which is a master regulator of cellular metabolism, plays a central role in the regulation of autophagy and a pivotal role in cancer." (PMID 33426544, 2020). "PI3K/Akt and the mammalian target of rapamycin (mTOR) signaling pathway is crucial to cell growth, cell metabolism, and survival and is the most frequently dysregulated pathway in cancer." (PMID 34766113, 2020). "Recently, the combination of autophagy inhibitors and PI3K/AKT/mTOR pathway inhibitors has been reported to enhance cell death in various cancers." (PMID 33123479, 2020). "Upregulation of the PI3K/AKT/mTOR pathway and increased glucose consumption via glycolysis offer advantages to cancer cells during normoxia as well as hypoxia." (PMID 32076440, 2020). "Many previous studies have shown that natural substances have the ability to suppress the PI3K/Akt/mTOR signaling pathway in several cancer cells, thus, targeting the PI3K/Akt/mTOR signaling pathway is a key strategy for the suppression of cancer." (PMID 32075054, 2020). "In fact, our experiments show that metabolic compounds are most effective in cancer cells in which autophagy is blocked by high-level mTOR signaling and that mTOR inhibition reduces their anti-cancer activity." (PMID 32943635, 2020). "The Akt/mTOR pathway triggers gene expression and enzyme activity, promoting aerobic glycolysis in both normal and cancer cells." (PMID 33262773, 2020).